LINC01018 (long independently transcribed non-coding RNA 1018)
Synonyms: SRHC
Gene: Long non-coding RNA gene on chromosome 5 (6,582,135 to 6,613,722, forward strand). Ensembl gene ENSG00000250056.
Diseases named in the same sentence as LINC01018 in open-access papers:
LINC01018 is named in the same sentence as 9 diseases in open-access papers, as found by Europe PMC text mining. Sharing a sentence is not in itself a finding about the gene and the disease. The quoted sentences say what the papers report.
liver cancer (2 papers, 2021 to 2023). An epithelial or non-epithelial malignant neoplasm that arises from the liver. "The mechanisms were subsequently further illustrated in this study, as we additionally found that miR‐942‐5p could bind to LINC01018 which is a newly identified lncRNA and plays an important regulatory role in liver cancer and liver diseases." (PMID 36550594, 2023). "Moreover, studies have shown that LINC01018 plays critical roles in HBV-induced liver cancer via ceRNA networks." (PMID 34692847, 2021).
glioma (1 paper, 2023). A benign or malignant brain and spinal cord tumor that arises from glial cells (astrocytes, oligodendrocytes, ependymal cells). "The results confirmed that LINC01018 overexpression not only inhibited the growth of glioma cells but also downregulated miR‐942‐5p expression and upregulated KNG1 expression, while LINC01018 knockdown and miR‐942‐5p mimic did the opposite." (PMID 36550594, 2023). "All these discoveries reflected that LINC01018 regulated the proliferation of glioma cells by targeting miR‐942‐5p." (PMID 36550594, 2023). "Here, we discovered that LINC01018 regulated the migration, invasion, proliferation, and cell cycle distribution of glioma cells by targeting miR‐942‐5p to alter epithelial‐mesenchymal transition (EMT) or proliferation‐related proteins." (PMID 36550594, 2023). "In a word, the results in this study authenticated that LINC01018 overexpression could inhibit the proliferation, migration, and invasion of glioma cells and the growth of glioma in nude mice by targeting the miR‐942‐5p/KNG1 axis." (PMID 36550594, 2023). "Silenced LINC01018 or KNG1 and miR‐942‐5p mimic enhanced the migration, invasion, and proliferation of glioma cells and regulated the expressions of metastasis‐related and proliferation‐related genes." (PMID 36550594, 2023). "Among them, the expressions of MALAT1, LINC01018, and MEG3 were lower in glioma, and the three were discovered to be the lncRNAs that possibly targeted miR‐942‐5p." (PMID 36550594, 2023).
hepatocellular carcinoma (1 paper, 2021). A malignant tumor that arises from hepatocytes. "The overexpression of LINC01018 leads to decreased proliferation and increased apoptosis in hepatocellular carcinoma and it is associated with overall survival." (PMID 33499129, 2021).
ovarian carcinoma (1 paper, 2021). A malignant neoplasm originating from the surface ovarian epithelium. "It is likely that LINC01018 serves a similar function in ovarian cancer." (PMID 33499129, 2021).
prostate carcinoma (1 paper, 2024). A carcinoma that arises from epithelial cells of the prostate gland. "miR-182 is also upregulated in prostate cancer tissues and cells, and lncRNA LINC01018 (which targets miR-182) was shown to regulate its expression." (PMID 39095540, 2024).
tumor (3 papers, 2018 to 2023). "Compared with the normal group, the expression levels of the most significant four lincRNAs (LINC01088, LINC01018, LINC01436 and LINC00243) were remarkably down-regulated in the tumor group, and the down-regulation of LINC01088 was the most marked." (PMID 29440672, 2018).
LINC01018 also shares sentences with these, for which no sentence is quoted: cancer (1 paper); liver diseases (1); non-alcoholic fatty liver disease (1).